TF (transferrin)
Diseases named in the same sentence as TF in open-access papers (continued):
Sharing a sentence is not in itself a finding about the gene and the disease.
ischemia (4 papers, 2017 to 2024). A hypoperfusion of the BLOOD through an organ or tissue caused by a PATHOLOGIC CONSTRICTION or obstruction of its BLOOD VESSELS, or an absence of BLOOD CIRCULATION. "The acidic environment caused by the ischemia can promote the dissociation of Fe2+ from transferrin, leading to increased extracellular Fe2+ levels, which in turn promotes increased iron uptake by neurons." (PMID 37752806, 2024). "We used 68Ga‐citrate as the probe for PET scan and biodistribution to investigate the level of TF influx and distribution in brain after ischemia–reperfusion injuries." (PMID 37480159, 2023). "On the other hand, overexpression of enkephalin and transferrin in MSC-generated exosomes showed robust neuroprotection after ischemia, because enkephalin has a neuroprotective effect, and transferrin receptors were highly expressed in the BBB." (PMID 32962207, 2020). "We showed that MF, HF, and total TF were significantly reduced in the 6h-ischemia group, which could be restored by KDZ injection." (PMID 28056927, 2017).
liver dysfunction (4 papers, 2019 to 2025). "On the one hand, the decrease in TF and TIBC was associated with the reduction in ALB and the prolongation of PT, indicating that liver dysfunction in PLA leads to insufficient synthesis of TF, which in turn caused a decrease in TIBC." (PMID 41280746, 2025). "Patients with ferritin > 390 ng/mL had a higher systemic inflammation level (WBC, NEUT%), liver dysfunction (ALT, AST, TBIL, LDH, ALB), iron metabolism disorders (TF, TIBC) and partly biochemical dysfunction (BUN)." (PMID 41280746, 2025).
lung diseases (4 papers, 2016 to 2025). "A previous study showed that patients with hyperinflammatory pulmonary disease with acute respiratory distress syndrome had increased transferrin levels." (PMID 37237739, 2023). "NP functionalization with transferrin may enhance NP-based therapeutic strategies for lung diseases." (PMID 33732602, 2021). "Because ferritin is a positive acute phase reactant and transferrin is a negative acute phase reactant, the acute phase response, which typically accompanies respiratory and lung diseases, also contributes to these changes." (PMID 40559821, 2025).
lupus nephritis (4 papers, 2016 to 2024). Glomerulonephritis in the context of systemic lupus erythematosus. "Clinical studies suggest that several proteins related to iron metabolism, including transferrin, serve as urinary biomarkers of lupus nephritis." (PMID 33015091, 2020). "Whether changes in urinary transferrin filtration and excretion represent an epiphenomenon or an accomplice to renal injury in lupus nephritis remains a tantalizing question." (PMID 33015091, 2020). "Of clinical relevance, urinary transferrin excretion is increased in both adult and pediatric lupus nephritis patients with active disease, and was recently included in a combinatorial biomarker panel found to predict decline of renal function in lupus nephritis patients." (PMID 28993663, 2017). "Whether renal iron deposition also occurs in lupus nephritis patients is unknown, although urinary biomarker studies suggest that the kidney is exposed to abnormal levels of proteins related to iron metabolism, including transferrin." (PMID 33015091, 2020). "Increased urinary excretions of transferrin, ferritin and NGAL in lupus nephritis patients provide evidence that the tubules of lupus nephritis patients have increased exposure to iron, which could facilitate renal iron accumulation and injury." (PMID 28993663, 2017). "Our findings of increased urinary transferrin excretion once albuminuria has developed in the MRL/lpr model in the current study and in NZBWF1 mice previously are congruent with clinical reports of increased urinary transferrin excretion in lupus nephritis patients." (PMID 33015091, 2020).
meningioma (4 papers, 2012 to 2023). A generally slow growing tumor attached to the dura mater. "In a small series of studies, 99mTc-TF uptake in meningiomas was correlated with cellular proliferative activity (assessed either immunohistologically by the Ki-67 index or by flow cytometry) and tumor grading." (PMID 22623896, 2012). "Likewise, meningiomas with higher proliferation index tended to exhibit increased 99mTc-TF uptake." (PMID 22623896, 2012). "The combination of TF and FN1 has been identified as one of the important pair features and showed good classification of meningioma grades." (PMID 37770851, 2023). "AKT1 meningiomas displayed high relative levels of HTRA1 and transferrin genes relative to KLF4 tumors, while KLF4 tumors overexpressed CEACAM6, DEGS2, and TSPAN12 relative to AKT1 tumors." (PMID 36937440, 2023). "Interestingly, a combination of Transferrin (TF) and FN1 along with TF and APOB showed better segregation as serum markers for meningioma grades." (PMID 37770851, 2023). "Anaplastic meningiomas tended to exhibit a higher radiotracer uptake as compared to typical ones without any overlapping of 99mTc-TF uptake between them." (PMID 22623896, 2012).
metastatic cancer (4 papers, 2021 to 2025). A carcinoma which has spread from the original site of growth to another anatomic site. "ORs for the association between a metastatic cancer and iron levels were near 1, the adjusted ORs ranging from 1.12 for serum iron and 0.97 for transferrin saturation, with wide 95% confidence intervals." (PMID 38112642, 2024). "Furthermore investigated for focused drug delivery in brain malignancies or metastatic cancers, where both tumor selectivity and effective cellular absorption are vital, are multi-functional ligand systems such as combining folic acid with transferrin." (PMID 40508696, 2025). "TF expression in metastatic cancer cells may be upregulated due to inflammation and hypoxia." (PMID 37205313, 2023). "Therefore, in the observed tissues, SPARCL1 was most highly expressed in normal colorectal tissues, and CDH2 had the highest expression in normal liver tissues and liver metastatic cancer tissues, while CP, HP, TF, and SERPINA5 with the most highly expressed in normal liver tissues." (PMID 34422629, 2021). "We also observed CDH2, CP, HP, TF, and SERPINA5 were upregulated in liver metastatic cancer tissues and downregulated in primary cancer tissues; whereas SPARCL1 exhibited the opposite expression pattern." (PMID 34422629, 2021).
myopia (4 papers, 2017 to 2025). "Furthermore, TMT analysis and PRM validation revealed that the expression of ferritin light chain (FTL, P02792) and ferritin heavy chain (FTH1, P02794) was negatively associated with myopia development, while the expression of serotransferrin (TF, P02787) was positively related to myopia status." (PMID 34660571, 2021). "Such expression changes were evident, particularly in the late myopia dataset where a wide range of genes linked with oxidative stress were either up-regulated (GPX1, GSTA3, MT-4, APOA1, OTUB, PTGDS, HSPB1, HSPB2) or down-regulated (XHD, SLC40A1, TF, SOD3, HPGDS, BCMO1)." (PMID 28852117, 2017). "Among the validation results, the abundance of TF was increased in the high myopia group, while FTL and FTH1 expression were both reduced in the high myopia group compared to the low myopia group." (PMID 34660571, 2021). "The TF gene and protein from choroid could be a regulator of myopic eye growth, as evidence showed an increase in mRNA levels in the recovering retina, retinal pigment epithelium (RPE) and choroid of a chick form-deprivation myopia (FDM) model." (PMID 39408973, 2024). "Additionally, up-regulation of TF has been detected in the chick vitreous after LIM treatment, further suggesting that TF could be an early indication of ocular elongation or myopia progression." (PMID 39408973, 2024).
oral cancer (4 papers, 2014 to 2024). "The genome wide transcription factor enrichment profile from ENCODE repository revealed a few prospective TF candidates for regulation of CARM1 expression in oral cancer such as E2F4, CTCF, YY1 and cMyc etc.." (PMID 31217904, 2019). "The sensitivity of the transferrin-based ELISA for oral cancer prediction was 100% for patients with stage T1 oral cancer, 86.6% for stage T2 and 100% for stage T3/T4." (PMID 36412636, 2022). "This suggests that salivary transferrin may be a biomarker for the detection of the early stage of oral cancer." (PMID 36412636, 2022). "Due to the direct contact between saliva and oral cancer lesions, various salivary proteomes have been reported in the literature as potential biomarkers for oral cancer detection such as interleukin-8 (IL-8), tumour necrosis factor-alpha, and salivary transferrin." (PMID 25276835, 2014). "Although recent studies support the potential role of salivary transferrin for the diagnosis of oral cancer, it is not enough to be satisfied with a few limited studies." (PMID 37964689, 2024).
peripheral arterial disease (4 papers, 2009 to 2024). A disorder of the arteries supplying the upper and lower extremity and the visceral organs. "According to these epidemiological studies, high systemic iron levels, monitored by serum ferritin levels or transferrin saturation, positively correlated with increased risk of myocardial infarction cardiovascular disease, peripheral arterial disease (PAD), and mortality rates." (PMID 24847266, 2014).
pulmonary hypertension (4 papers, 2011 to 2024). Increased pressure within the pulmonary circulation due to lung or heart disorder. "TF is also expressed in pulmonary plexiform lesions in humans and in a rat model of severe pulmonary hypertension." (PMID 22194859, 2011).
renal carcinoma (4 papers, 2018 to 2023). A carcinoma arising from the epithelium of the renal parenchyma or the renal pelvis. "However, some of these genes, such as RNASET2, TF, and ZIC2, were already known to have an oncogenic role in the tumorigenesis, progression, and metastasis of renal cancer." (PMID 36463181, 2022). "Other research has shown that transferrin (TF) and beta-1,4-N-acetyl-galactosaminyltransferase 1 (B4GALNT1) are highly expressed in patients with ccRCC, and B4GALNT1 may affect the occurrence and progression of renal cancer through the Hippo signaling pathway." (PMID 36483738, 2022).
renal dysfunction (4 papers, 2016 to 2025). "In contrast, recipients of long-stored RBCs had higher transferrin saturation and plasma iron levels, elevated markers of oxidative stress and renal dysfunction, and increased proinflammatory cytokines and immunomodulatory metabolites." (PMID 40608427, 2025).
retinal detachment (4 papers, 2011 to 2022). An eye emergency condition which may lead to blindness if left untreated. "Exogenous transferrin can thus help in iron clearance to decrease cell death induced by retinal detachment." (PMID 35251467, 2022). "The increase in both iron and TF has been shown to be correlated with poor visual acuity in murine models of retinal detachment." (PMID 35251467, 2022). "We speculate that both retinal detachment and SiO may have impacts on transferrin concentration." (PMID 34926578, 2021). "Indeed, pathological subretinal fluid following retinal detachment has a very different protein composition from normal IPM, containing significant amounts of serum proteins such as albumin, transferrin, and gammaglobulin subunits." (PMID 22065916, 2011).
squamous cell carcinoma (4 papers, 2011 to 2018). A carcinoma arising from squamous epithelial cells. "Invasiveness of TF-GFP (squamous cell carcinoma) cells was strongly enhanced by co-expression of BRACHYURY and SOX2." (PMID 30453543, 2018). "In TF (squamous cell carcinoma) cells, forced expression of BRACHYURY showed nearly the same changes in gene expression as in ACCS-M GFP cells." (PMID 30453543, 2018). "In the present study, we showed that overexpression of BRACHYURY upregulated NANOG expression slightly, but failed to promote self-renewal capacity not only in ACCS GFP (adenoid cystic carcinoma) cells but also in TF GFP, a squamous cell carcinoma cell line." (PMID 30453543, 2018). "In human squamous cell carcinoma, the activation of EGFR stimulates TF expression, which is modulated by E-cadherin in vitro, and an E-cadherin-neutralizing antibody led to the upregulation of TF expression." (PMID 21245964, 2011).
Trichiasis (4 papers, 2018 to 2025). Inversion and rubbing of the eyelashes against the globe of the eye. "At the end of 2020, in the 39 EUs surveyed, the prevalence of TF in 1-9-year-olds was ≥5% in 11 EUs and the prevalence of trichiasis unknown to the health system in individuals aged ≥15 years was ≥0.2% in 25 EUs." (PMID 38320117, 2024).
type 1 diabetes (4 papers, 2014 to 2025). "Clinical outcomes of islet transplantation have been directly correlated with TF expression levels, suggesting that TF blockade represents a novel therapeutic avenue to enhance the survival rate of type 1 diabetes islet transplantation." (PMID 38111575, 2023). "Previously, we proposed a novel application of the bifunctional fusion protein design through the introduction of proinsulin-transferrin (ProINS-Tf) fusion protein as a liver-specific protein prodrug to achieve a glucose-lowering effect in type 1 diabetic mice." (PMID 32382087, 2020). "Thus, normoalbuminuric and normotensive children and adolescents with type 1 diabetes have elevated urinary VEGF, AGT, and transferrin levels, which may indicate the development of diabetic kidney disease before the development of albuminuria." (PMID 40362266, 2025). "The present study demonstrates that rats with type 1 diabetes induced by streptozotocin showed elevated levels of cholesterol, HDL, triglycerides, blood glucose, GPT, alkaline phosphatase, and urea and reduced levels of iron and transferrin 30 days following exposure." (PMID 24971142, 2014).
varicocele (4 papers, 2022 to 2025). A condition characterized by the dilated tortuous veins of the spermatic cord with a marked left-sided predominance. "In twenty men (6 fertile men, 8 with varicocele, 6 with leukocytospermia) seminal phospholipase A2, iron, cholesterol, transferrin, estradiol, ferritin, testosterone, and sperm membrane fatty acids were detected." (PMID 35052611, 2022). "Among the altered proteins, several exosomal proteins including Annexin A2 (ANXA2), Transferrin (TF), Kinesin‐1 heavy chain (KIF5B), and semenogelin 1 (SEMG1) were found to be consistently expressed differently in the seminal plasma of patients with unilateral varicocele." (PMID 41222141, 2025).
Zinc deficiency (4 papers, 2013 to 2025). A deficiency of the essential metal Zinc; an essential cofactor for many enzymes. "To validate the findings, we further analyzed the expression of 14 TF genes using qRT-PCR under control, iron, copper, and zinc deficiency, as well as zinc excess conditions." (PMID 32107545, 2020).
adenoma (3 papers, 2014 to 2023). A neoplasm arising from the epithelium. "Another biomarker study utilising FIT, FC, transferrin and lactoferrin showed poor discrimination (AUC = 0.67) for the prediction of adenomas." (PMID 37781155, 2023). "The result was a list of 257 TF genes with z-scores ≥ 2 in the hypergeometric enrichment test, reflecting gene expression changes in adenomas amounting to at least 2 standard deviations from the mean expression change." (PMID 24472434, 2014). "Hierarchical clustering analysis of the 34 tissue samples based on the expression levels of these TF genes showed clear separation of the adenomas and normal mucosa samples." (PMID 24472434, 2014). "Parallel MetaCore analysis of the original gene set identified 793 TF genes whose interaction networks were enriched for genes displaying significant differential expression in adenomas, as compared with normal mucosa samples." (PMID 24472434, 2014). "However, a similarly large proportion of TF genes were dysregulated only in carcinomas, which indicates that this program undergoes an important change across the adenoma-to-cancer transition." (PMID 24472434, 2014).
adenomyosis (3 papers, 2022 to 2026). The growth of endometrial tissue inside the muscular wall of the uterine corpus. "However, due to the retrospective nature of the study, some data that may affect coagulation parameters, such as iron and transferrin, CA125 and CA199, adenomyosis subtype, uterine leiomyoma subtype, and menstrual coagulation parameters, could not be completely obtained." (PMID 35956000, 2022).
amyloid (3 papers, 2018 to 2023). "To address these challenges and enhance the precision of delivery into brain regions affected by amyloid aggregation, we proposed a transferrin-conjugated nanoparticle-based drug delivery system." (PMID 37834402, 2023). "Hemopexin (HPX) and transferrin (Tf) were detected in the serum samples from amyloid-positive mice and were also found in amyloid deposits via immunohistochemistry, but serum samples from amyloid-negative mice did not contain HPX and Tf." (PMID 29288430, 2018). "Finally, we identified VUS in genes for which alterations have been reported in the literature in patients with ATTRwt amyloidosis, as it is the case of the CP gene, responsible for ceruloplasmin, and TF gene, coding for transferrin." (PMID 37784196, 2023).
amyotrophic lateral sclerosis (3 papers, 2014 to 2023). Amyotrophic lateral sclerosis (ALS) is a neurodegenerative disease characterized by progressive muscular paralysis reflecting degeneration of motor neurons in the primary motor cortex, corticospinal tracts, brainstem and spinal cord. "This study posits that biochemical blood parameters, including total protein, albumin, urea, creatinine, transferrin, and overall lymphocyte count, may serve as an effective tool for assessing the nutritional status of patients with amyotrophic lateral sclerosis (ALS)." (PMID 38313408, 2023).
antiphospholipid syndrome (3 papers, 2012 to 2023). A disorder caused by the presence of autoantibodies directed against phospholipids, causing a hypercoaguable state, which may result in blood clots, stroke, heart attack, and in women, significant pregnancy-related complications, including miscarriage and still birth. "Studies of antiphospholipid syndrome have demonstrated that autoantibodies can exert an influence on TF expression on either monocytes or endothelial cells." (PMID 35008670, 2021).
atrial fibrillation (3 papers, 2022). A disorder characterized by an electrocardiographic finding of a supraventricular arrhythmia characterized by the replacement of consistent P waves by rapid oscillations or fibrillatory waves that vary in size, shape and timing and are accompanied by an irregular ventricular response. "Genetically instrumented transferrin levels [OR 0.90; 95% CI 0.86–0.97; p = 0.006] were inversely correlated with atrial fibrillation." (PMID 35637428, 2022). "Genetically instrumented serum iron [OR 1.09; 95% confidence interval (CI) 1.02–1.16; p = 0.01], ferritin [OR 1.16; 95% CI 1.02–1.33; p = 0.02], and transferrin saturation [OR 1.05; 95% CI 1.01–1.11; p = 0.01] had positive effects on atrial fibrillation." (PMID 35637428, 2022).
Blindness (3 papers, 2013 to 2025). Blindness is the condition of lacking visual perception defined as a profound reduction in visual perception. "The role of these pathogens in the persistence of TF post-MDA therefore warrants further study; the key question is whether TF in these circumstances is likely to progress to conjunctival scarring and blindness." (PMID 23936573, 2013).
breast tumors (3 papers, 2020 to 2023). "The coexpression of ZEB1 and ERα in breast tumor cells in situ confirms our findings with tissue culture cells regarding the possibility to form a ZEB1-ERα TF complex in cells with partial EMT states." (PMID 35440541, 2022). "We predict that presence of hemoglobin and transferrin in the PC of CA played a role for its ability to deliver fluorescence siRNA to the breast tumors in our animal model." (PMID 32927738, 2020).